MARK2 (microtubule affinity regulating kinase 2)
Diseases named in the same sentence as MARK2 in open-access papers:
MARK2 is named in the same sentence as 261 diseases in open-access papers, as found by Europe PMC text mining. Sharing a sentence is not in itself a finding about the gene and the disease. The quoted sentences say what the papers report.
breast cancer (74 papers, 2008 to 2026). A primary or metastatic malignant neoplasm involving the breast. "In Luminal A breast cancer, higher expression of MARK2, NUAK2, and PAK1 was significantly associated with improved survival in both pre- and post-chemotherapy groups." (PMID 34084284, 2021). "While some of the top candidates have been previously reported to play a role in cancer (FLNB, MAP3K7, NFYA, and ESYT2) others were identified to be breast cancer-relevant for the first time (NEDD4L, MARK2, ABI1)." (PMID 38664594, 2024). "In all breast cancer combined, high expression of LKB1, AMPK, LYK5, MARK1, MARK2, NUAK2, PAK1 (both probe sets), SIK1, SIK2, BRSK1, BRSK2, SNRK, and QSK was positively correlated with improved survival compared to low expression of these genes." (PMID 34084284, 2021). "Importantly, we were also able to confirm, by RT-PCR, the aberrant AS regulation of PACSIN2, DIAPH1, MARK3, ADD3, MAP3K7, and MARK2 in RNA extracts from two human tumor breast cancer samples tissues and two non-pathological tissues." (PMID 34202984, 2021).
prostate carcinoma (26 papers, 2004 to 2025). A carcinoma that arises from epithelial cells of the prostate gland. "Another miRNA, miR-520a binds to the 3' UTR of target genes including Microtubule Affinity Regulating Kinase 2 (MARK2), Estrogen Receptor 1 (ESR1) at early-stage cancer and Suppressor of Zeste 12 (SUZ12) during advance-stage and ESR1 during CRPC progression of prostate cancer." (PMID 31756185, 2019). "The role of MARK2 with respect to prostate cancer was not yet been studied, while previous reports showed that ESR1 play protective roles in prostate cancer development, though still unknown." (PMID 31756185, 2019).
Alzheimer disease (24 papers, 2013 to 2025). A progressive, neurodegenerative disease characterized by loss of function and death of nerve cells in several areas of the brain leading to loss of cognitive function such as memory and language. "The MARK2 gene has been reported to be associated with Alzheimer's disease and bipolar disorder." (PMID 34953473, 2022). "Hence, common variants of MARK2 gene could be investigated as the candidate modulators of lithium therapeutic action in Alzheimer’s disease and bipolar disorder." (PMID 34953473, 2022). "It is suggested that the protein MARK2 is involved in early phosphorylation of tau, a protein that when phosphorylated plays an important role in Alzheimer’s disease." (PMID 38365790, 2024). "For example, an Alzheimer’s disease variant in the TREM2 gene (rs75932628) was also correlated with amyotrophic lateral sclerosis, while a variant in the MARK2 gene (rs10792421) was associated with Alzheimer’s disease and bipolar disorder." (PMID 36873109, 2023). "Hyperphosphorylation of Tau by microtubule affinity regulating kinase 2 (MARK2) was reported as a key event in disrupting the MT binding of Tau and promoting its abnormal aggregation, which is closely associated with Alzheimer’s disease (AD)." (PMID 30587819, 2018). "A protein kinase microtubule-affinity regulating kinase 2 (MARK2) also plays key roles in several cell processes underlying neurodegenerative diseases, such as Alzheimer's disease, by phosphorylating tau and detaching it from microtubules." (PMID 23533695, 2013). "Here, we describe the reciprocal regulation of a kinase, the microtubule affinity-regulating kinase 2 (MARK2), and an acetyltransferase, CREB-binding protein (CBP), two enzymes known to extensively modify tau proteins in the progression of Alzheimer’s disease." (PMID 35469920, 2022).
lung carcinoma (23 papers, 2008 to 2025). "For example, MARK1 is amplified in various cancer types, such as breast and liver cancer, and MARK2 is upregulated in lung cancer." (PMID 35017636, 2022). "For instance, MARK2 is involved in the PI3K/AKT/NF-κB signaling pathway and its upregulation leads to resistance to cisplatin in osteosarcoma and lung cancer by decreasing apoptosis." (PMID 40332117, 2025). "Baicalin suppresses protein expression of microtubule affinity-regulating kinase 2 (MARK2) and Akt in A549/DDP cells, which are involved in cell proliferation and the pathogenesis of lung cancer." (PMID 34069141, 2021).
Insulin resistance (22 papers, 2013 to 2025). Increased resistance towards insulin, that is, diminished effectiveness of insulin in reducing blood glucose levels. "Identifying dysregulated phosphosites common to multiple insults reveals subnetworks containing non-canonical regulators of insulin action, such as MARK2/3, and causal drivers of insulin resistance." (PMID 36808134, 2023).
Parkinson disease (15 papers, 2013 to 2026). A progressive degenerative disorder of the central nervous system characterized by loss of dopamine producing neurons in the substantia nigra and the presence of Lewy bodies in the substantia nigra and locus coeruleus. "Moreover, the T313M mutation of PINK1, an important regulator of mitochondrial trafficking, abolishes its phosphorylation by a protein kinase MARK2, exhibits toxic effects in neurons, and is involved in neurodegeneration in Parkinson’s disease (PD)." (PMID 30244175, 2018).
pancreatic cancer (13 papers, 2003 to 2024). "In pancreatic cancer cells, the serin-threonine kinase MARK2 is activated in response to paclitaxel treatment, a microtubule disrupting agent." (PMID 36762207, 2023).
ovarian carcinoma (12 papers, 2008 to 2026). A malignant neoplasm originating from the surface ovarian epithelium. "Among the dependencies associated with a kinase-substrate interaction, we found that mutation of STK11 (LKB1) in ovarian cancer models was associated with an increased dependency upon MARK2 (p = 2 × 10−3), an LKB1 substrate." (PMID 26947069, 2016).
Obesity (11 papers, 2011 to 2025). Accumulation of substantial excess body fat. "Mice with disrupted genes for Mark2 or Mark3, which are other members of the AMPK family, have been found to be resistant to diet-induced obesity due to enhanced glucose-utilization in the brown adipose tissue." (PMID 22662228, 2012). "Mice lacking MARK2 have an increased rate of glucose disposal in response to exogenous insulin, increased glucose tolerance, and are resistant to diet-induced obesity." (PMID 22206009, 2011).
amyotrophic lateral sclerosis (10 papers, 2016 to 2025). Amyotrophic lateral sclerosis (ALS) is a neurodegenerative disease characterized by progressive muscular paralysis reflecting degeneration of motor neurons in the primary motor cortex, corticospinal tracts, brainstem and spinal cord. "Both MARK2 and PKCδ are activated via phosphorylation in proteotoxicity-associated neurodegenerative mouse models and in human patients with amyotrophic lateral sclerosis (ALS)." (PMID 33705388, 2021).
non-small cell lung carcinoma (9 papers, 2016 to 2025). A group of at least three distinct histological types of lung cancer, including non-small cell squamous cell carcinoma, adenocarcinoma, and large cell carcinoma. "MARK2 is overexpressed in cisplatin-resistant cell lines and expression level of MARK2 correlate with resistance to cisplatin in non-small cell lung cancer." (PMID 35757381, 2021). "MARK2/4 may promote the Warburg effect and cell growth of non-small cell lung cancer through AMPKα1/mTOR/HIF-1α signaling pathway." (PMID 39588377, 2024).
epilepsy (7 papers, 2016 to 2026). A brain disorder characterized by episodes of abnormally increased neuronal discharge resulting in transient episodes of sensory or motor neurological dysfunction, or psychic dysfunction. "We find that three out of eight autistic offspring with variants in MARK2 report epilepsy, two out of eight report Tourette syndrome and seven out of eight have evidence of cognitive impairment." (PMID 35982159, 2022). "In P5 Par1b/MARK2 knockout mice, microglia exhibit shortened primary and secondary processes but increased branching, which is reminiscent of hypertrophic microglia observed in autism spectrum disorders (ASD), aging, or epilepsy." (PMID 30654821, 2019).
bipolar disorder (5 papers, 2018 to 2022). A disorder of the brain that causes unusual shifts in mood, energy, activity levels and the ability to carry out day-to-day tasks. "Further studies are needed to study the association of tau phosphorylation by regulatory genes, such as the MARK2 gene, with bipolar disease to confirm previous findings and attribute them to bipolar disorder." (PMID 34953473, 2022). "Regarding the importance of MARK2 gene in the pathophysiology of bipolar disorder and also in the lithium’s mechanism of action, the association of one of these gene variants, rs10792421, was investigated with different responses to lithium treatment in bipolar type 1 patients." (PMID 34953473, 2022).
Anxiety (4 papers, 2023 to 2024). Intense feelings of nervousness, tension, or panic often arise in response to interpersonal stresses. "Additionally, the loss of MARK2 produces substantial impairments in learning and memory, reduced anxiety, and defective social behavior." (PMID 39436150, 2024).
autoimmune disease (4 papers, 2010 to 2023). A disorder resulting from loss of function or tissue destruction of an organ or multiple organs, arising from humoral or cellular immune responses of the individual to their own tissue constituents. "T cells lacking expression of MARK2 are hyper-responsive to TCR triggering with increased cytokine production and MARK2-null mice develop autoimmune disease, indicating that MARK2 is required for immune homeostasis." (PMID 19830737, 2010). "According to our research, the mammalian immune system’s stability depends on the MARK2 protein kinase, so aberrant expression could possibly result in autoimmune diseases and pregnancy complications." (PMID 37901230, 2023).
Cognitive impairment (4 papers, 2018 to 2024). Abnormal cognition is characterized by deficits in thinking, reasoning, or remembering. "We first analyzed MARK2 levels in cortical brain samples from 12-month-old WT and symptomatic tau P301S (PS19) transgenic mice that display tau pathology, neuronal loss, and cognitive impairments." (PMID 35469920, 2022).
ovarian tumors (4 papers, 2014 to 2024). "Of note, MARK2 was also identified as IKKε-dependent lethal gene, but only 4 out of 506 TCGA ovarian tumors showed overexpression (2 fold change) of MARK2, which functions in cell polarity and regulation of microtubule dynamics." (PMID 25474241, 2014).
tauopathy (4 papers, 2014 to 2024). Neurodegenerative disorders involving deposition of abnormal tau protein isoforms (tau proteins) in neurons and glial cells in the brain. "Overall, these findings suggest that MARK2 dysfunction and altered downstream regulation of MARK2 substrates is associated with the progression of tauopathy." (PMID 35469920, 2022). "Similar to tauopathy mice, we found significantly lower MARK2 protein levels in AD brains, again consistent with a negative correlation between MARK2 levels and AD progression." (PMID 35469920, 2022). "Whether the levels of other tau kinases change in parallel with MARK2 in tauopathy models will require further investigation." (PMID 35469920, 2022). "Also, more target areas of MARK2 on tau in transgenic mice of the Tauopathies model emphasize the importance of MARK2 in this disease." (PMID 34953473, 2022). "Furthermore, active MARK2 co-localizes with NFTs in AD brain, and MARK2 target sites on tau are elevated in transgenic mouse models of tauopathy, emphasizing the importance of MARK2 in this disease." (PMID 24847206, 2014). "MARK2 knockdown has no impact on DAPK1-induced tau hyperphosphorylation, but the MARK2-induced tau phosphorylation and microtubule destabilization are potentiated by DAPK1 in neurons as DAPK1 overexpression enhances MARK2 activity in tauopathy." (PMID 38195518, 2024). "Based on our initial findings, we expected an inverse relationship between MARK2 and tauopathy progression, though no prior studies had documented MARK2 protein changes in AD brain." (PMID 35469920, 2022).
Infertility (2 papers, 2023). "Because PRL is essential for maintaining luteal function and progesterone secretion, PRL deficiency caused by MARK2 dysfunction may lead to infertility in females." (PMID 37901230, 2023).
sarcoma (2 papers, 2021 to 2025). A usually aggressive malignant neoplasm of the soft tissue or bone. "Interestingly, a recent study reported that concomitant inhibition of both MARK2 and MARK3 is required to prevent YAP/TAZ function in diverse carcinoma and sarcoma contexts, highlighting the redundant nature of MARK family members." (PMID 40869130, 2025).
Autoimmunity (1 paper, 2008). The occurrence of an immune reaction against the organism's own cells or tissues. "The decreased expression of MARK2 may be associated with the generation of autoimmunity in coeliac disease." (PMID 18691394, 2008). "Mouse studies suggest that one of the genes, MAP/microtubule affinity-regulating kinase 2 (MARK2), plays a role in maintenance of immune system homeostasis and prevention of autoimmunity." (PMID 18691394, 2008).
Immune Thrombocytopenic Purpura (1 paper, 2020). "For example, a mild virus-activated protein in our network is the serine/threonine kinase MARK2, which is one of the targets of the drug Fostamatinib in the treatment of Rheumatoid Arthritis and Immune Thrombocytopenic Purpura." (PMID 32244779, 2020).
luminal B breast carcinoma (1 paper, 2021). A biologic subset of breast carcinoma defined by low to moderate expression of genes characteristic of luminal epithelial cells including estrogen receptor (ER), and high expression of GGH, LAPTM4B, and CCNE1. "In Luminal B breast cancer, AMPK expression was positively associated with survival in both pre- and post-chemotherapy groups, while MARK2 was negatively associated with survival in both groups." (PMID 34084284, 2021).
myelofibrosis (1 paper, 2023). A partial or complete replacement of the bone marrow stroma by fibrous tissue. "MARK2 and MARK3 have been approved as drug targets for the treatment of cancer and myelofibrosis." (PMID 37730114, 2023).
cancer (365 papers, 2003 to 2026). A tumor composed of atypical neoplastic, often pleomorphic cells that invade other tissues. "Phosphorylation at Thr208 of MARK2 was located in the activation loop, which may lead to loss of cell polarity through interfering with microtubule stability and to an unfavorable prognosis, which has been observed in other cancers." (PMID 40075679, 2025). "Members of the MARK subfamily, including MARK2, 3 and 4, regulate the Hippo kinase cassette in diverse models including Drosophila, mice and human cancer cell lines by phosphorylating MST1/2, SAV and, as found in a recent study, NF2 and YAP/TAZ." (PMID 40869130, 2025). "MARK2 plays vital roles in modulating directional cancer cell migration, which is crucial for cancer metastasis." (PMID 36542699, 2022). "However, we focused our attention on PACSIN2, DIAPH1, MARK3, ADD3, MAP3K7, and MARK2 cassette exons as these events were validated in both normal and cancer cell lines and in non-pathological and tumor breast specimens." (PMID 34202984, 2021). "Thus, inhibiting MARK2/3 could represent an alternative approach to target YAP/TAZ activity in YAPon cancers, although there are currently no small molecular inhibitors of these kinases." (PMID 40440076, 2025).
tumor (279 papers, 2002 to 2026). "Among the 38 tumor tissues with both upregulation of MARK2 and downregulation of WW45, a high proportion of them had reduced p-YAP (34 of 38) and p-MOB1 (31 of 38)." (PMID 37843276, 2023). "Notably, we observed robust reduction of WW45 (i.e., ratios of T/N <0.5; 53 of 60) and dramatically increased MARK2 (i.e., ratios of T/N >2), especially among WW45-low tumor tissues (38 of 53)." (PMID 37843276, 2023). "We confirmed an aberrant increase of cassette exon skipping in tumor specimens for PACSIN2 exon 8, DIAPH1 exon 2, FGFR1OP2 exon 4, MARK3 exon 16, DST exon 93, LMO7 exon 10, and RBM5 exon 7, whereas ADD3 exon 13, MAP3K7 exon 12, and MARK2 exon 15 were preferentially included in tumor specimens." (PMID 34202984, 2021).
infection (24 papers, 2009 to 2025). The state of being infected such as from the introduction of a foreign agent such as serum, vaccine, antigenic substance or organism. "Cluster 4 included sites presenting decreased phosphorylation intensities due to the infection of RBCs (Y359 of Band 3, S1381 of Tensin-1, S365 and S366 of Serine/threonine-protein kinase MARK2)." (PMID 33842387, 2021). "We previously identified MARK1, MARK2 and MARK3 kinases as interaction partners of Orf9b35 and ongoing studies will reveal their role in infection and the innate response." (PMID 34942634, 2022).
neurodegenerative disease (15 papers, 2013 to 2025). A disorder of the central nervous system characterized by gradual and progressive loss of neural tissue and neurologic function. "Furthermore, the activation of the PKCδ-MARK2-eIF2α pathway in ALS mouse models and human patients associated with protein misfolding suggests that this stress signaling may be important for the pathogenesis of relevant neurodegenerative diseases." (PMID 33705388, 2021).
metabolic disorders (9 papers, 2013 to 2025). "As a result, MARK2-knockout mice had reproductive defects, imbalance in the immune system, weak learning/memory ability, growth retardation, metabolic disorders, and a variety of other symptoms." (PMID 27046191, 2016).
neurological diseases (8 papers, 2011 to 2024). "However, despite its genetic association with several neurological disorders, the in vivo impact of MARK2 on neuronal connectivity and cognitive functions remains unclear." (PMID 39436150, 2024).
MARK2 also shares sentences with these, for which no sentence is quoted: melanoma (62 papers); colorectal cancer (14); diabetes (14); gastric cancer (14); hepatocellular carcinoma (12); Peutz-Jeghers syndrome (12); glioma (11); metastatic melanoma (10); ataxia telangiectasia (9); osteosarcoma (9); schizophrenia (9); thyroid cancer (9); cardiac hypertrophy (8); colon carcinoma (8); Hypertension (8); pulmonary fibrosis (8); viral infection (8); cardiovascular diseases (7); multiple myeloma (7); neuroblastoma (7); depression (6); lung adenocarcinoma (6); lymphoma (6); autism spectrum disorder (5); glioblastoma (5); hematologic malignancies (5); mantle cell lymphoma (5); osteoporosis (5); papillary thyroid carcinoma (5); Type 2 Diabetes (5).
A further 201 diseases each share a sentence with MARK2 in 4 papers or fewer.